IL17A (interleukin 17A)
Diseases named in the same sentence as IL17A in open-access papers (continued):
Sharing a sentence is not in itself a finding about the gene and the disease.
psoriasis (continued). "Moreover, patients with active disease exhibited significantly higher levels of IL-17A, IL-23, and IL-22 than those with stable psoriasis, suggesting that these cytokines might play an important role in disease exacerbation." (PMID 40699767, 2025). "Therefore, CD274 (PD-L1) may be involved in regulating the activity of the IL-17a and IL-23 pathways in psoriasis, affecting autoimmune reactions and the occurrence of inflammation." (PMID 40557155, 2025). "Taken together, our findings indicate that, while dysregulated IL-17a contributes to pathology in autoimmune diseases such as psoriasis or arthritis in humans, in canine leishmaniosis, IL-17a may serve a protective role in promoting an effective immune response." (PMID 41310729, 2025). "Furthermore, inflammatory cytokines relevant to psoriasis pathogenesis, including Il17a, Tnfa, and Il1b, as well as neutrophil‐attracting chemokines, such as Cxcl1 and Csf3, were significantly upregulated at the mRNA level in Fads2‐silenced skin lesions compared to controls." (PMID 40878384, 2025). "Notably, IL17A expression exhibited psoriasis-specific restriction to T-cell populations." (PMID 40959079, 2025). "Moreover, cases of patients with psoriasis or other chronic inflammatory systemic diseases treated with IL-17A inhibitors, IL-12/23 inhibitors, IL-23 inhibitors or TNF-α inhibitors developing eczematous paradoxical reactions, as well as paradoxical psoriasis, have been reported." (PMID 39161766, 2024). "Consequently, the immune‐inflammatory mechanisms are involved in both psoriasis and depression, and IL‐17A may exert a central role in triggering depression symptoms in the pathological condition." (PMID 39660880, 2024). "In addition, a possible explanation for why IL-17A correlates with atherosclerosis only in psoriasis patients, despite similar levels in healthy individuals, could involve the chronic inflammatory environment characteristic of psoriasis." (PMID 39104857, 2024). "Additionally, target cells in the vascular system of psoriasis patients might be more sensitive to IL-17A due to disease-specific changes, such as altered gene and protein expression." (PMID 39104857, 2024). "Additionally, the anti-IL-17A aptamer was able to ameliorated psoriasis symptoms." (PMID 39045230, 2024). "Among anti-IL-17 biologic agents, inhibitors, for the treatment of psoriasis are available ixekizumab and secukinumab, which are IL-17A inhibitors; brodalumab, an inhibitor of the IL-17A receptor; and bimekizumab, a monoclonal IgG1 antibody that inhibits both IL-17A and IL-17F." (PMID 39634792, 2024). "DP in psoriasis may be due to the inhibitory effect of interleukin-17A on melanogenesis." (PMID 38956402, 2024). "Several studies have revealed that IL-17A is an essential cytokine for activating KCs, leading to a positive feedback loop that induces the production of additional cytokines and chemokines, amplifying inflammation, and one that IL-17A plays a central role in the pathogenesis of psoriasis." (PMID 39352743, 2024). "Similarly, levels of IL-17A were elevated in both PsA and psoriasis patients compared to healthy." (PMID 38292069, 2024). "In addition, Trm cells produced by migrating memory T cells preferentially express IL-17A, and in psoriasis, CD8+ Trm cells that produce IL-17A may constitute a pathogenic group in the skin." (PMID 38779662, 2024). "Based on our findings, we hypothesize that during the progression of psoriasis, Th1 and Th17-derived cytokines (such as TNFα and IL17A) may induce PARP2 in keratinocytes, which may turn down aromatase activity and estrogen synthesis in keratinocytes that may trigger NF-κB activation." (PMID 37351597, 2023). "Notably, IL-17A and IL-23 are key drivers of psoriasis development." (PMID 37920459, 2023).
psoriasis (continued). "Reflecting the decreased DC numbers after systemic IL-17A blockade in the immunohistochemistry experiment, both mature and semimature DC numbers were decreased in posttreatment psoriasis lesional skin compared to pretreatment psoriasis lesional skin in scRNA-seq data." (PMID 37781383, 2023). "Furthermore, Il17a−/−mice injected with recombinant mouse IL-25 still induced psoriasis." (PMID 37005677, 2023). "IL-17A treated STAT3 overexpressing mouse model might serve as an animal model for psoriasis." (PMID 37465147, 2023). "In psoriasis, the long-standing proof for the use of baicalin alternative medicine was established via in vivo studies, where common symptoms such as epidermal thickening, erythema, and desquamation backed with IL-17A, IL-22, and IL-23 level were significantly reduced after treatment." (PMID 37371141, 2023). "Thus, IL-17A secretion by T-cells does not only induce the expression of IL-36α and IL-36γ in various cell types but also synergistically induce the expression of various cytokines and chemokines driving the progression of psoriasis." (PMID 38162658, 2023). "Moreover, results of a clinical trial carried out in northern Italy on COVID‐19 patients with psoriasis and treated with IL‐17A inhibitors showed a relatively low hospitalization rate (four out of 5206), suggesting a protective role of IL‐17A inhibitors against COVID‐induced cytokine storm." (PMID 37193304, 2023). "To date, an association of the IL17A gene with psoriasis has not yet been established." (PMID 37628670, 2023). "Moreover, as Tong and coworkers suggested, TNF-a, IL-17A, and IL-23 could potentially be used as biomarkers for the measurement and monitoring of depression and anxiety in individuals with psoriasis." (PMID 37240864, 2023). "Quantification of the percentage of Th17 cells and the expression levels of IL17A/F using scRNA-seq data showed they were significantly higher in the lesional skin than in the non-lesional skin, both of which are considered as hallmarks in the pathogenesis of psoriasis." (PMID 39872300, 2023). "Moreover, the IL17A signaling of keratinocytes has an important contribution to the development of psoriasis in mice, suggesting that besides T cells, keratinocytes are also critical players in psoriasis pathogenesis." (PMID 37351597, 2023). "However, the dominant immune response in psoriasis is T helper 17 (Th17), whose characteristic cytokines are interleukin 17A (IL-17A), interleukin 17F (IL-17F), interleukin 21 (IL-21), interleukin 22 (IL-22), interleukin 29 (IL-29), interleukin 8 (CXCL-8), and tumor necrosis factor α (TNF-α)." (PMID 38001807, 2023). "Notably, NF-κB could bind to the promoter of IL-17A and transactivate it in HaCaT cells, indicating a critical role of NF-κB in psoriasis." (PMID 36839031, 2023). "Furthermore, CXCL12 is induced in ECs in response to psoriasis-related stimuli including IL-17A." (PMID 37736772, 2023). "We stimulated sc and shP2 HPV-Kers with the combination of IL17A and TNFα, as it was previously established that the synergistic action of IL17A and TNFα on keratinocytes induces such transcriptomic changes that show a massive correlation with the psoriasis gene signature." (PMID 37351597, 2023). "In addition, an in silico study also showed that linalool may have good binding against several psoriasis targets such as IL-17, IL-22, IL-23, IL-17a, IL-17b, IL-17f, IL-22α1, and IL-22α2." (PMID 35684387, 2022). "To evaluate whether our self-assembled RSE can be used in disease modeling in response to pathogenic cytokines involved in inflammatory skin diseases, we attempted to build a psoriatic skin model using IL-17A, which is a major cytokine in psoriasis pathogenesis." (PMID 35745784, 2022). "These clinical observations implicit that IL-17A could be a crucial link for psoriasis and atherosclerosis and IL-17A-induced inflammatory responses are the major contribution to the pathogenesis of comorbid psoriasis and atherosclerosis." (PMID 35514987, 2022).
psoriasis (continued). "The mechanism and function of the potential IL-17RC-only transduction of IL-17 signaling remains to be explored and may provide further insight into the development of therapeutic agents for autoimmune diseases, such as psoriasis, where a blockade of IL-17A and IL-17RA showed significant efficacy." (PMID 36140808, 2022). "Indeed, antibodies neutralizing IL17A have been shown to be powerful therapeutics for human diseases and positive clinical trial data has been reported in psoriasis, psoriatic arthritis, ankylosing spondylitis with now approved drugs such as secukinumab/Cosentyx and ixekizumab/Taltz11–13." (PMID 36028520, 2022). "Thus, our discussion will focus on the role of IL-17A in comorbid psoriasis and atherosclerosis." (PMID 35514987, 2022). "In clinical practice, IL‐17A antibodies (Secukinumab and Ixekizumab), and IL‐17 receptor A inhibitors (Brodalumab) could reduce the K17 expression, which are effective and safe therapies for psoriasis." (PMID 35665210, 2022). "While direct quantification of free IL-17A levels is challenging during treatment, the findings from this study reveal the value to assess tissue site TE and provide quantitative predictions to facilitate future drug development via IL-17A suppression in psoriasis." (PMID 35548359, 2022). "Finally, the patient was treated with the IL-17A inhibitor secukinumab for psoriasis." (PMID 36324078, 2022). "In addition to exhibiting psoriasis-like features, Asian AD patients often show a robust Th17 response (IL-17A, IL-19 and S100A12) in the skin lesions and are more susceptible to S. aureus colonization, perhaps due to a lack of AMPs, damage to the skin barrier and dysbiosis of the microbial ecology." (PMID 36314037, 2022). "However, it is meaningful that the self-assembled RSE model is very responsive to cytokine stimuli and some of the psoriasis phenotypes can be induced using IL-17A alone in a self-assembled 3D skin model composed of normal-derived fibroblasts and keratinocytes." (PMID 35745784, 2022). "Therefore, a neutrophil–keratinocyte axis in psoriasis may involve neutrophil-derived IL-17A and is an early target of IL-17A-directed therapies." (PMID 35401573, 2022). "The question whether IL-17A regulates Claudin-1 remains unanswered; findings that they are correlated should be met with caution: further prospective studies are required, especially in psoriasis." (PMID 35340911, 2022). "Remarkably, the combination of IL-17A and Claudin-1 (AUC: 0.741, p = 0.0067) almost performed identically to Claudin-1 alone (AUC: 0.741, p = 0.0045), while IL-17A (AUC: 0.590, p = 0.3126) had poor performance separating early-onset psoriasis from late-onset psoriasis." (PMID 35340911, 2022). "Similarly, previous studies have noted greater expression of mRNA encoding IL-17A or IL-17 in lesional than non-lesional biopsies of patients with psoriasis." (PMID 34945130, 2021). "Considering that dysregulated lipid metabolism has been regarded as the critical factor in cardiovascular diseases, the recovery of lipid metabolites in psoriasis patients indicates that IL-17A mAbs might have the potential protective effects against cardiovascular comorbidities." (PMID 33602246, 2021). "In addition, the risk of AEs but not SAEs was increased by IL-17A inhibitors in patients with psoriasis and psoriatic arthritis." (PMID 33432451, 2021). "Therefore, our results suggested that L-THE downregulates the production of IL-23 and chemokines, and attenuates the IMQ-induced psoriasis like skin inflammation by inhibiting the activation of NF‐κB and IL-17A signaling pathway, and promotes the propanoate metabolism." (PMID 34381369, 2021). "Involvement of IL17A in inflammation and autoimmune disease has been widely illustrated since its discovery on 2005, and abnormal expressions of IL17A are found in development of several diseases including psoriasis, rheumatoid arthritis and multiple sclerosis." (PMID 33509093, 2021).
psoriasis (continued). "Besides Th1, Th2 and Treg (regulatory) cells, Th17 cells and its secreted cytokine IL-17A have been shown to play a central role in the pathogenesis of various immune-mediated inflammatory diseases such as psoriasis, rheumatoid arthritis, multiple sclerosis and inflammatory bowel disease." (PMID 34239010, 2021). "A study in psoriasis and control patients, had earlier found highly increased levels of both IL-25 mRNA and protein in keratinocytes of psoriatic lesions, compared to non-lesional or control samples; furthermore, these IL-25+ cells outnumbered IL-17A+ cells in papillary dermis." (PMID 34201664, 2021). "Th17 cells, as well as Th1 cells and keratinocytes, secrete TNF-α, IFN-γ, IL-1β, IL-6, IL-12, IL-17A, IL-22, IL-23 participating in pathophysiologic processes of psoriasis and current biological therapies as T cell-directed agents have demonstrated excellent efficacy in psoriasis." (PMID 33685393, 2021). "However, both IFN-γ and IL-17A are known to contribute to psoriasis-related inflammation." (PMID 33986690, 2021). "Interestingly, IL17A has been described as eliciting atypical M2-like and mixed M1 and M2 phenotypes in macrophages isolated from an inflammatory context, such as atherosclerosis and psoriasis." (PMID 33802061, 2021). "IL-19 could amplify IL-17A effects on keratinocytes in psoriasis." (PMID 33681365, 2021). "Given the key role of the TNF-α/IL-23/IL-17A axis in the pathogenesis of psoriasis, it could be hypothesized that polycyclic aromatic hydrocarbons (PAHs), such as TCDD, via AHR activation have a potential impact on the development or aggravation of the disease." (PMID 33921372, 2021). "Additionally, several cytokines, such as tumor necrosis factor (TNF)-α, interleukin (IL)-1β, IL-12, IL-17A, IL-22, and IL-23, upregulate the production of reactive oxygen species and the hyperproliferative keratinocyte state seen in psoriasis, and are shown to play a role in some malignancies." (PMID 34685480, 2021). "Rising inflammatory factors such as IL-17A may promote an increase in intracellular cholesterol and then inflow circulation, leading to a parallel rise in blood cholesterol levels, which may be one of the reasons for psoriasis and dyslipidemia comorbidity." (PMID 33762935, 2021). "Therefore, our results demonstrated that L-THE significantly decreases the levels of IL-23 and chemokines, and attenuates IMQ-induced psoriasis like skin inflammation by inhibiting the activation of NF‐κB and IL-17A signaling pathways, and promoting the propanoate metabolism." (PMID 34381369, 2021). "In addition, CD4+CD25+Foxp3+ Tregs could differentiate into IL-17A–producing Th17 cells in psoriasis and aggravate its symptoms by inducing imbalance of Th17/Treg, activating effecting T cells and immune response in skin." (PMID 33981308, 2021). "In order to further investigate whether the potential mechanism of glycyrrhizin for the treatment of psoriasis involves the regulation of the inflammatory response, ELISA was used to detect the expression of IL-17A and IFN-γ in the serum of wild-type mice or IMD mice, with or without treatment." (PMID 34044769, 2021). "Thus, IL-17A-producing CD103+ TRM cells may have an influence on the future clinical course of psoriasis." (PMID 33633737, 2020). "Several IL-17A blockers, including the anti-IL-17A monoclonal antibodies secukinumab, ixekizumab, and bimekizumab, and the anti-17RA monoclonal antibody brodalumab, are approved for some immune-mediated inflammatory diseases, such as psoriasis, psoriatic arthritis, and ankylosing spondylitis." (PMID 33597953, 2020). "Finally, early clinical studies with bimekizumab, a dual IL‐17A and IL‐17F neutralizing antibody, have shown rapid and profound clinical responses in psoriasis 21 and PsA 20 patients suggesting an unappreciated role for IL‐17F in addition to IL‐17A in promoting inflammation." (PMID 31850514, 2020).
psoriasis (continued). "Recently, T cell-targeted monoclonal antibodies such as the anti-IL-17A agent secukinumab, anti-CD4 monoclonal antibody, and cytotoxic T lymphocyte-associated antigen 4-immunoglobulin have demonstrated significant therapeutic efficacy in the treatment of psoriasis." (PMID 32817748, 2020). "If anti-IL-17A therapies influence the development of RORγt+ ILCs, these therapies might have unintended outcomes in patients with chronic colitis that are distinct from those in patients with psoriasis." (PMID 31941937, 2020). "This study indicated that IL-17A might be a link between vascular disease and psoriasis." (PMID 32587871, 2020). "Moreover, blocking IL-17A and IL-23 prevented psoriasis-related thrombosis in preclinical studies." (PMID 33117403, 2020). "In order to investigate the role played by IL-17A and IL-36 cytokines in the activation of skin EC, expression of IL-17 and IL-36 receptors by HDMECs was analyzed, together with possible modulation of this expression by inflammatory cytokines present in the psoriasis microenvironment, such as TNF-α." (PMID 32352958, 2020). "In summary, the current study may suggest that Notch-Hes1 signaling is participated in the pathogenesis of psoriasis by regulating IL-17A+γδ+T cell expression and IL-17A secretion, and blocking Notch-Hes1 signaling may be a new strategy for immunotherapy of psoriasis." (PMID 32454795, 2020). "Even though IL-17A and IL-17F are the most important of the IL-17 family members involved in the pathogenesis of psoriasis, IL-17E is also increased in keratinocytes from the psoriasis plaque and seems to play a proinflammatory role, as it is implicated in macrophage activation." (PMID 30744173, 2019). "Therefore, we hypothesized that either the long-term vascular inflammation or additional effects of IL-17A other than neutrophil infiltration contribute to the impaired vascular function in the murine model of psoriasis." (PMID 31396305, 2019). "Finally, recent clinical trials testing the safety and efficacy of monoclonal antibodies targeting IL-17A and IL-23 in SpA, psoriasis, psoriatic arthritis and Crohn's disease have been very encouraging and have increased the therapeutic options for these diseases." (PMID 30941119, 2019). "In the case of IL-17A-producing neutrophils, they are increased in the peripheral blood of patients with asthma who are allergic to fungus, as well as in the plaques of psoriasis patients, and in the joints of patients with ankylosing spondylitis but not in those of patients with osteoarthritis." (PMID 31388340, 2019). "Thus, anti-IL-17A therapy not only improves skin manifestations of psoriasis, but also cardiovascular inflammation as well as metabolic factors and different domains of psoriatic arthritis (PsA) including peripheral arthritis, enthesitis, dactylitis, and axial involvement." (PMID 32010143, 2019). "Additionally, a strong link between psoriasis and cardiovascular comorbidities has been noted, for which IL-17A may be an important factor." (PMID 31474979, 2019). "Then, growth factors and relevant cytokines (IL-17A, TNF-α, and IL-1β) in psoriasis activate mTOR and promote keratinocyte hyperproliferation and inhibit differentiation, which might be the mechanism underlying the PI3K/Akt pathway and psoriasis." (PMID 31824416, 2019). "In addition to IL-17A, our study suggests that some pathogenic Tregs may also produce more TNF-α in psoriasis skin, potentiating the effects of IL-17A and contributing further to the inflammatory cascade." (PMID 30054515, 2018). "Moreover, the serum levels of IL-17A are positively correlated with the severity of psoriasis." (PMID 29232931, 2017). "Finally, IL-17A itself became a therapeutic target in psoriasis." (PMID 27158469, 2016).